SUV39H1 (SUV39H1 histone lysine methyltransferase)
Diseases named in the same sentence as SUV39H1 in open-access papers (continued):
Sharing a sentence is not in itself a finding about the gene and the disease.
diabetes (5 papers, 2020 to 2023). "We demonstrate that diabetes increases the recruitment of Suv39H1 at Rac1 promoter, which assists in the recruitment of Dnmt1, initiating an active DNA methylation-hydroxymethylation and transcriptional activation." (PMID 34238980, 2021). "Key parameters were confirmed in an in vivo model using retinal microvessels from mice, that were administered Suv39H1-siRNA or Dnmt1-siRNA (intravitreally) soon after induction of streptozotocin-induced diabetes." (PMID 34238980, 2021). "This study reveals the novel role of Suv39h1 in VSMCs of diabetes and suggests its potential role as a therapeutic target in diabetic vascular injury." (PMID 31736204, 2020). "Suv39h1, a histone methyltransferase, plays a protective role against myocardial injury in diabetes." (PMID 31736204, 2020). "Therefore, Suv39h1 may constitute a promising therapeutic target in vascular complications involving diabetes mellitus." (PMID 31736204, 2020). "Regulation of Suv39H1 by its siRNA prevented diabetes-induced upregulation of Rac1 transcription; Rac1 gene transcripts in diabetic mice receiving Suv39H1-siRNA were not significantly different from those obtained from normal mice." (PMID 34238980, 2021). "Targeting Suv39h1 not only inhibits VSMC migration and proliferation as well as neointima formation, but it also promotes re‐endothelialization after vascular injury in diabetes." (PMID 31736204, 2020).
glioblastoma (5 papers, 2015 to 2025). The most malignant astrocytic tumor (WHO grade IV). "Similarly, H3K9me3, which is catalyzed by the histone-lysine N-methyltransferase SUV39H1 (also known as KMT1A), has been associated with the repression of differentiation pathways in glioblastoma CSCs." (PMID 40099195, 2025). "H1x and nuclear SUV39H1 expression were correlated with improved overall survival in the entire cohort (p = 0.0034 and p = 0.0004 respectively) as well as in glioblastomas (p = 0.0030 and p = 0.0113 respectively)." (PMID 25602259, 2015). "In the present investigation, we demonstrate for the first time that the expression of these two transcriptionally repressive HKMTs is up-regulated in astrocytic tumors with glioblastomas displaying elevated cytoplasmic SUV39H1 and SETDB1, but intriguingly lower nuclear SUV39H1." (PMID 25602259, 2015).
Hyperglycemia (5 papers, 2012 to 2023). An increased concentration of glucose in the blood. "Suv39H1-siRNA also attenuates hyperglycemia-induced increase in Rac1 expression, further supporting the role of H3K9me3 at Rac1 promoter in DNA methylation." (PMID 34238980, 2021). "Hyperglycemia has been shown to decrease the expression of SUV39H1 to promote renal fibrosis." (PMID 34769288, 2021). "Regulation of histone methylation enzyme, Suv39H1, by its specific siRNA inhibits hyperglycemia-induced increase in 5hmC at Rac1 promoter and ameliorates increase in Rac1 gene transcripts, implying a close cross-talk between DNA methylation and H3K9 methylation." (PMID 34238980, 2021). "It well known that p21WAF1 is transcribed at high levels after acute kidney injury, and inhibition of methyltransferase SUV39H1 expression has been found to attenuate hyperglycemia-induced fibronectin and p21WAF1 expression, and to accelerate hyperglycemia-induced cell hypertrophy." (PMID 34769288, 2021). "SUV39H1 is responsible for trimethylation at H3K9 to H3K9me334; our results show that its expression and binding at Rac1 promoter are increased in hyperglycemia, and silencing of Suv39H1 attenuates increase in 5hmC, which is a product of dynamic DNA methylation." (PMID 34238980, 2021).
liver cancer (5 papers, 2016 to 2025). An epithelial or non-epithelial malignant neoplasm that arises from the liver. "SUV39H1 is also believed to be involved in the development of liver cancer in a considerable number of patients infected with hepatitis B virus." (PMID 38650654, 2024). "The H3K9 tri-methyltransferase genes, SETDB1 and SUV39H1, have been shown to be overexpressed in cancers, such as lung and liver cancers." (PMID 27572307, 2016). "Notably, our findings suggest that miR24‐2 alters several related genes (pHistone H3, SUZ12, SUV39H1, Nanog, MEKK4, pTyr) and accelerates progression of liver cancer cells through Pim1 activation." (PMID 32030886, 2020). "Besides, amplification of the SETDB1 gene was found in lung and liver cancers, and SETDB1 and SUV39H1 were negatively regulated by miR-29 and miR-125b, respectively." (PMID 27572307, 2016).
cervical cancer (4 papers, 2020 to 2024). A primary or metastatic malignant neoplasm involving the cervix. "In cervical cancer cells, cells with low levels of SUV39H1 protein have a higher migratory ability in vitro, and SUV39H1 knockdown in vitro enhances cancer cell migration." (PMID 36185333, 2022). "Collectively, these results indicated that SUV39H1 participate in the regulation of DNMT3A through changing H3K9me3 expression level in cervical cancer cells." (PMID 32699524, 2020). "Overexpression SUV39H1 also associated with increased methylation level of HAVCR2 and LGALS9 which in turn caused Tim-3 and galectin-9 expression decreased in cervical cancer." (PMID 32699524, 2020). "Taken together, above results revealed that SUV39H1 regulated the expression of DNMT3A through elevating H3K9me3 level at the DNMT3A promoter in cervical cancer cells." (PMID 32699524, 2020). "In cervical cancer, SUV39H1 knockout enhance the migration ability of cervical cancer cells." (PMID 38650654, 2024). "Suv39H1 promotes the proliferation of cervical cancer cells via the AKT pathway." (PMID 35619625, 2022). "Activation the expression of SUV39H1 may potentially be an effective approach to increase the efficacy of immune cells against cervical cancer." (PMID 32699524, 2020). "After have been determining the baseline levels of DNA methylation on HAVCR2 and LGALS9 promoter regions among cervical cancer cell line, evaluation whether SUV39H1 mediated DNA methylation through DNMT3A is required for HAVCR2 and LGALS9 transcription." (PMID 32699524, 2020). "SUV39H1 up-regulates H3K9me3 expression at the DNMT3A promoter region, which in turn induced expression of DNMT3A in cervical cancer." (PMID 32699524, 2020). "In summary, the present study highlights the role of SUV39H1 and DNMT3A in the DNA methylation regulation of Tim-3 and galectin-9 in cervical cancer." (PMID 32699524, 2020). "SUV39H1 targeted DNMT3A by increasing the level of H3K9me3 at the DNMT3A promoter region so that repressed Tim-3 and galectin-9 expression by DNA methylation in cervical cancer." (PMID 32699524, 2020). "As persistent HR-HPV infection contributes to almost all cervical cancer cases, we attempted to explore whether HR-HPV oncogenes E6 and E7 participated in SUV39H1 mediated DNA methylation in SiHa and HeLa cells." (PMID 32699524, 2020). "Here, we identified a novel function of SUV39H1 regulates DNMT3A expression through elevating H3K9me3 level at the DNMT3A promoter region, which could mediate Tim-3 and galectin-9 expression through DNA methylation in cervical cancer." (PMID 32699524, 2020).
clear cell renal cell carcinoma (4 papers, 2022 to 2024). "For example, SUV39H1 silencing was shown to promote ferroptosis, as demonstrated in clear cell renal cell carcinoma." (PMID 39519018, 2024). "The inhibition of SUV39H1 in renal clear cell carcinoma can induce iron accumulation and lipid peroxidation, leading to the ferroptosis of cancer cells." (PMID 38017386, 2023). "However, in clear cell renal cell carcinoma (ccRCC), suppressor of variegation 3−9 homolog 1 (SUV39H1), an HMT that deposits H3K9me3, has been found to protect cells against ferroptosis." (PMID 37229485, 2023).
lupus (4 papers, 2010 to 2022). "In systemic lupus erythematosus (SLE), RFX1 downregulated IL17A, CD70, and CD11a expression by recruiting DNMT1, HDAC1, and SUV39H1 to alter epigenetic modifications in CD4+ T cells from patients with lupus." (PMID 30857550, 2019).
bladder cancer (3 papers, 2020 to 2025). "Interestingly, a previous study in bladder cancer stem cells showed that SUV39H1 maintains the self-renewal of these cells by repressing the transcription factor GATA3, leading to the upregulation of STAT3 and maintaining stemness." (PMID 40059829, 2025).
gastric cancer (3 papers, 2016 to 2022). A primary or metastatic malignant neoplasm involving the stomach. "GKN1 down-regulation in gastric cancer tissues was shown to be associated with high levels of H3K9triMe and with the recruitment of SUV39H1 to the GKN1 promoter, suggesting the presence of an epigenetic transcriptional complex that negatively regulates GKN1 expression in gastric tumors." (PMID 28129645, 2017). "miR-125a-5p, a recognized prognostic factor in gastric cancer, regulates SUV39H1 (KMT1A) and prevents angiogenesis." (PMID 35087589, 2022). "Our present study documents the overexpression of Suv39H1 and histone tri-methylated H3K9 in gastric carcinoma." (PMID 28129645, 2017). "In conclusion, utilizing several specimens from patients with gastric carcinoma, we found that GKN1 expression is significantly reduced in dysplasia and tumor gastric mucosa, and is inversely correlated with the recruitment of H3K9triMe and Suv39H1 to the GKN1 promoter." (PMID 28129645, 2017). "Thus, SETDB2 expression and function detected in our study were similar to those of SETDB1 and SUV39H1 in cancers, suggesting that SETDB2 may have oncogenic functions and overexpression of SETDB2 play roles in gastric cancer progression." (PMID 27572307, 2016).
head and neck squamous cell carcinoma (3 papers, 2019 to 2024). A squamous cell carcinoma that arises from any of the following anatomic sites: lip and oral cavity, nasal cavity, paranasal sinuses, pharynx, larynx, and salivary glands. "The transcription level of SUV39H1 was increased in various cancer tissues, and the transcription level in head and neck squamous cell carcinoma tissues was significantly higher than that in control tissues." (PMID 38650654, 2024). "The transcription level of SUV39H1 in head and neck squamous cell carcinoma was significantly higher than that in control." (PMID 38650654, 2024). "The transcription of SUV39H1 is increased in head and neck squamous cell carcinoma, and the expression of SUV39H1 in OSCC is correlated T stage." (PMID 38650654, 2024). "In summary, our findings suggest that inhibition of SUV39H1 in head and neck squamous cell carcinoma may affect angiogenesis by regulating Notch1 expression." (PMID 38650654, 2024).
idiopathic scoliosis (3 papers, 2019 to 2023). A scoliosis with no known cause. "And the significantly increased expression of SUV39H1 in patients with idiopathic scoliosis can promote the proliferation chondrocytes and Alpinetin can improve colitis by decreasing the expression of SUV39H1." (PMID 38017386, 2023).
lung adenocarcinoma (3 papers, 2013 to 2022). A carcinoma that arises from the lung and is characterized by the presence of malignant glandular epithelial cells. "Compared to SUV39H1, the amplification percentage of SUV39H2 was much higher throughout the various stages of lung adenocarcinoma; guided by which, we found that the CNA and the expression of SUV39H2 shared a positive relation, leading to an explanation of its overexpression." (PMID 30348215, 2018). "Our results suggest that overexpression of HMGA1, E2F6, IRF1, and TFDP1 and downregulation or no expression of SUV39H1, RBL1, and HNRPD in blood is suitable for diagnosis of lung adenocarcinoma and squamous cell carcinoma sub-types of NSCLC." (PMID 24564251, 2013).
myocardial infarction (3 papers, 2017 to 2023). Gross necrosis of the myocardium, as a result of interruption of the blood supply to the area, as in coronary thrombosis. "Additionally, SUV39H1 inhibition has been found to protect mice from myocardial infarction by preventing SIRT1 transcriptional repression." (PMID 37758732, 2023).
neuroblastoma (3 papers, 2007 to 2022). Neuroblastoma (NB) is the most common solid, extracranial childhood tumor. "Neither expression of SETDB1 nor SUV39H1/SUV39H2 could be associated with the increased telomeric H3K9me3 in ALT-positive neuroblastomas." (PMID 33627664, 2021). "Cluster 3 (Crlf3 and Mier 1) and Cluster 4 (Atp5c1, Suv39h1, Immt, Slca6) are not over-expressed in neuroblastoma cells lines and seem unlikely to play a role in neuroblastoma." (PMID 17397536, 2007).
Obesity (3 papers, 2022 to 2024). Accumulation of substantial excess body fat. "Reduced expression of SUV39H1 in visceral fat arteries from obese subjects was correlated with accumulation of ROS and the excessive oxidative stress, leading to obesity-related vascular disease." (PMID 36193085, 2022). "Interestingly, among alterations to the three H3K9-modifying enzymes, the downregulation of SUV39H1 induced by obesity is central to H3K9 modification on the p66Shc promoter, leading to ROS-induced endothelial dysfunction and the development of atherosclerosis." (PMID 35340204, 2022). "We found that six genes (Sacm1l, Junb, Bmi1, Erbb4, Dkc1, and Suv39h1) are neuron stress-related genes and increased in the HFD-induced mice obesity model, Bmi1gene was identified as a key genes that can reflect the pathophysiology of obesity." (PMID 39717104, 2024). "Experiments have verified that the complex of SUV39H1, JMJD2C, and SRC-1 is recruited to the promotor of p66Shc and that JMJD2C and SRC-1 cannot influence the activity of SUV39H1, indicating that targeting SUV39H1 but not JMJD2C or SRC-1 will delay the development of obesity-induced atherogenesis." (PMID 35340204, 2022).
oral squamous cell carcinoma (3 papers, 2013 to 2024). "Although the significance of cytoplasmic SUV39H1 remains presently unknown, it has been recorded in oral squamous cell carcinoma in which only nuclear SUV39H1 was positively associated with stage." (PMID 25602259, 2015). "Here we investigated the effect of the suppressor of variegation 3–9 homolog 1 (SUV39H1) on tumor angiogenesis in oral squamous cell carcinoma (OSCC)." (PMID 38650654, 2024).
T-cell lymphoma (3 papers, 2013 to 2026). "Indeed, such an effect may be implied by the fact that double knockout of SUV39H1/H2 causes genomic instability, while SUV39H1 dependent senescence reportedly protects mice from Ras-driven invasive T-cell lymphoma." (PMID 25602259, 2015). "In a murine model of Ras-driven T cell lymphoma, SUV39H1-dependent senescent growth arrest prevents the onset of tumorigenesis; this senescence is likely dependent on H3K9 methylation on specific growth genes." (PMID 23705022, 2013).
viral infection (3 papers, 2017 to 2021). "IFI16 interacts with SUV39H1 and GLP to generate the IFI16/SUV39H1/GLP complex, and the complex is recruited to the KSHV genome, leading to the methylation of H3K9 during viral infection and latency." (PMID 34299198, 2021). "Cell proliferation analysis demonstrated that the number of cell divisions during the first 3 days after viral infection were not much different among the Suv39h1 dn iMEFs infected with an empty or expression vector for Suv39h1 proteins." (PMID 28760201, 2017). "Moreover, we found that Ad‐Suv39h1 infection increased the PCNA level by more than onefold, while LV‐Suv39h1 shRNA reduced the PCNA level by approximately 50%, as compared with control virus infection (P < .05)." (PMID 31736204, 2020).
adenoma (2 papers, 2013 to 2023). A neoplasm arising from the epithelium. "In some cases, these genes were uniquely up-regulated in residual tumors (e.g., Setd1a, Dyrk3), while in other cases the genes were up-regulated in both residual and untreated adenoma tumors (e.g., Suv39h1, Mll1)." (PMID 23520493, 2013).
alveolar rhabdomyosarcoma (2 papers, 2018 to 2024). A rapidly growing malignant mesenchymal neoplasm. "In alveolar rhabdomyosarcoma (ARMS), increased SUV39H1 levels were found to impair MyoD, blocking myogenic differentiation and growth arrest." (PMID 39766049, 2024).
atherosclerosis (2 papers, 2022 to 2024). A disease characterized by the build-up of fatty material and calcium deposition in the arterial wall resulting in partial or complete occlusion of the arterial lumen. "However, high p66Shc expression induced by alterations in histone modifications, such as decreased H3K4me2/3 regulated by SUV39H1 and JMJD2C, enhances the progression of ROS-dependent atherosclerosis in obese and overweight mice." (PMID 35340204, 2022).
cardiac hypertrophy (2 papers, 2019 to 2021). "SUV39H1 is known to differentially regulated, and its increased expression is reported to be associated with the development of cardiac hypertrophy." (PMID 33898535, 2021).
colitis (2 papers, 2018 to 2023). Inflammation of the colon. "In conclusion, NOR promoted Treg differentiation and then alleviated the development of colitis by regulating AhR/glycolysis axis and subsequent NAD+/SIRT1/SUV39H1/H3K9me3 signaling pathway." (PMID 29449535, 2018).
depression (2 papers, 2013 to 2020). "Third, although we demonstrated that the Mkp-1-PPARγ-SUV39H1 pathway functions as a stress-adaptation system in stress-induced depression, the executives of altered function of the Mkp-1-PPARγ-SUV39H1 pathway in stress-induced depression is unknown." (PMID 32504071, 2020).
epithelial ovarian cancer (2 papers, 2022 to 2024). "Interestingly, in ovarian cancer, high expression of SUV39H1 promotes the proliferation of cancer cells and leads to poor prognosis in patients (Li, Shao & Zhao, 2021)." (PMID 38650654, 2024). "Suv39H1 may regulate the proliferation and metastasis of epithelial ovarian cancer cells." (PMID 35619625, 2022).
esophageal cancer (2 papers, 2020 to 2025). A primary or metastatic malignant neoplasm involving the esophagus. "In esophageal cancer tissues, high expression of SUV39H1 is associated with poor prognosis." (PMID 41011559, 2025). "Further research revealed that GT could downregulate the expression of SUV39H1 in esophageal cancer cells, thereby inducing cellular ferroptosis." (PMID 41011559, 2025).
fibrosarcoma (2 papers, 2022 to 2025). A malignant mesenchymal fibroblastic neoplasm affecting the soft tissue and bone. "Also, we generated a new mouse strain, namely the Suv39h1-Flox*CD4-Cre, in which mice are KO for SUV39h1 only in T cells (see the section “Methods” for strain description), and we grafted them with the MCA-101 fibrosarcoma cell line, which is less immunogenic that the B16-F10-OVA." (PMID 35768432, 2022).
liver fibrosis (2 papers, 2023 to 2024). "For instance, we have previously shown that SUV39H1 skews phenotypic switch of quiescent hepatic stellate cells to promote liver fibrosis." (PMID 39603205, 2024).
nasopharyngeal carcinoma (2 papers, 2024 to 2025). A carcinoma arising from the nasopharyngeal epithelium. "In prostate and nasopharyngeal carcinoma, decreasing SUV39H1 expression inhibit the proliferation and invasion of tumor cells." (PMID 38650654, 2024). "Moreover, baicalin promoted suv39h1 splicing by enhancing RNA m6A methylation, resulting in anti-nasopharyngeal carcinoma (NPC) behavior." (PMID 40830264, 2025). "Baicalin promoted suv39h1 splicing by enhancing RNA m6A methylation, resulting in anti-nasopharyngeal carcinoma (NPC) behavior." (PMID 40830264, 2025).
progeria (2 papers, 2019). "A study using progeria mouse models, however, suggests that Suv39h1 exacerbates premature aging, with deletion of Suv39h1 associated with longer life." (PMID 30488545, 2019). "Depleting the H3K9me3 methyltransferase Suv39h1 in a progeria mouse model reduces H3K9me3 levels, delays senescence in progeroid cells, and extends lifespan, but whether perturbation of Suv39h1 can extend lifespan in healthy mice is not known." (PMID 31460700, 2019).
renal carcinoma (2 papers, 2022 to 2025). A carcinoma arising from the epithelium of the renal parenchyma or the renal pelvis. "In urologic cancers, SUV39H1 has been found to inhibit the occurrence of cell ferroptosis and promote the progression of renal cancer." (PMID 36147463, 2022).